CYSTM1 (cysteine rich transmembrane module containing 1)
Synonyms: C5orf32; ORF1-FL49
Tractability: Antibody: its Gene Ontology location is reachable by antibodies, with high confidence; UniProt predicts a signal peptide or a membrane-spanning region. PROTAC: ubiquitination databases record sites on it.
Gene: Protein-coding gene on chromosome 5 (140,175,072 to 140,282,052, forward strand). Ensembl gene ENSG00000120306.
Subcellular location: Membrane
Pathways (Reactome):
Immune System: Neutrophil degranulation
Gene Ontology:
Molecular function: protein binding
Cellular component: extracellular exosome; plasma membrane; tertiary granule membrane; membrane
Genetic constraint (gnomAD): Loss-of-function variants: 4 observed, 13.93 expected, observed/expected ratio (o/e) 0.29, 90% interval 0.14 to 0.66. The upper end of that interval is the gene's LOEUF score, 0.66, which puts it in group 2 of 6, group 1 being the genes least tolerant of losing a copy. Missense variants: 96 observed, 127.72 expected, observed/expected ratio (o/e) 0.75, 90% interval 0.64 to 0.89. Synonymous variants: 36 observed, 45.1 expected, observed/expected ratio (o/e) 0.8, 90% interval 0.61 to 1.05.
Homologues: Orthologues: chimpanzee CYSTM1 (100% identical), macaque CYSTM1 (99% identical), rabbit CYSTM1 (94% identical), pig CYSTM1 (79% identical), mouse Cystm1 (77% identical), guinea pig CYSTM1 (72% identical).
Diseases named in the same sentence as CYSTM1 in open-access papers:
CYSTM1 is named in the same sentence as 11 diseases in open-access papers, as found by Europe PMC text mining. Sharing a sentence is not in itself a finding about the gene and the disease. The quoted sentences say what the papers report.
melanoma (2 papers, 2011 to 2019). A malignant, usually aggressive tumor composed of atypical, neoplastic melanocytes. "With regard to the genes specifically up-regulated in the MCSP CTC fraction, the majority have been involved in metastasis (LOXL4, ST6GALNAC2, PYGL), tumour growth (PLK2, CYSTM1, GLUL), and/or melanoma biology (SEC31A, WIPI1, SKP1)." (PMID 30769764, 2019).
Sepsis (2 papers, 2023 to 2024). Sepsis is defined as life-threatening organ dysfunction caused by a dysregulated host response to infection. "As pediatric sepsis diagnostic indicators, CYSTM1 (AUC = 0.988), MMP8 (AUC = 0.973), and CD177 (AUC = 0.986) were investigated and demonstrated statistically significant differences (P < 0.05) and diagnostic efficacy in the validation set." (PMID 37115484, 2023). "This study concluded that CYSTM1, MMP8 and CD177 are pediatric sepsis diagnostic indicators." (PMID 37115484, 2023). "In the GSE13904 validation set, the expression of CYSTM1, MMP8, and CD177 was considerably higher in the pediatric sepsis group than in the control group (P < 0.01)." (PMID 37115484, 2023). "The candidate hub genes (CD177, CYSTM1, and MMP8) were identified, and the nomogram was constructed for pediatric sepsis diagnosis." (PMID 37115484, 2023). "Although CYSTM1 has not been subjected to considerable research in sepsis until now, it possesses the potential to be an effective novel therapeutic target once further validation has been carried out." (PMID 37115484, 2023).
Amoebiasis (1 paper, 2023). "Amoebiasis, antifolate resistance, malaria, neutrophil extracellular trap formation, and sulfur metabolism had significant enrichment in the high CYSTM1 subgroup." (PMID 38013304, 2023).
asthma (1 paper, 2023). "In contrast, allograft rejection, asthma, autoimmune thyroid disease, primary immunodeficiency, and protein export had significant enrichment in the low CYSTM1 subgroup." (PMID 38013304, 2023).
Huntington disease (1 paper, 2015). Huntington disease (HD) is a rare neurodegenerative disorder of the central nervous system characterized by unwanted choreatic movements, behavioral and psychiatric disturbances and dementia. "The five genes (PROK2, ZNF238, AQP9, CYSTM1 and ANXA3) that were validated independently in both cohorts present a candidate biomarker panel for stage determination and therapeutic readout in Huntington's disease." (PMID 25626709, 2015).
primary immunodeficiency (1 paper, 2023). "Primary immunodeficiency was enriched in subgroups with low expression of CYSTM1 and low expression of RNASE1." (PMID 38013304, 2023).
septic shock (1 paper, 2023). Shock caused by infection; frequently caused by gram negative bacteria, although some cases have been caused by other bacteria, viruses, fungi, and protozoa; characterized by fever, chills, tachycardia, tachypnea, and hypotension. "CD177, CLEC5A, CYSTM1, MCEMP1, MMP8, and RGL4 were identified as hub genes, which were of considerable value in the early diagnosis of septic shock patients." (PMID 37359526, 2023). "In addition, higher expression levels of CD177, CLEC5A, CYSTM1, MCEMP1, MMP8, and RGL4 messenger RNA (mRNA) were observed in peripheral blood mononuclear cells (PBMCs) isolated from septic shock patients than from healthy donors." (PMID 37359526, 2023).
tumor (2 papers, 2019 to 2025). "The gene subsets identified within ADC-abundant cell sub-clusters, including Epi_10_CYSTM1, Tregs, pro-tumor TANs, and P/B_01_IGHA2, exert potential roles in promoting both the carcinogenesis and immunosuppression of ADC." (PMID 40066698, 2025).
CYSTM1 also shares sentences with these, for which no sentence is quoted: autoimmune thyroid disease (1 paper); cancer (1); malaria (1).